Y_RNA (Y RNA )
Gene: Miscellaneous RNA gene on chromosome 2 (20,480,844 to 20,480,955, forward strand). Ensembl gene ENSG00000200829.
Homologues: Orthologues: chimpanzee Y_RNA (97% identical), macaque Y_RNA (94% identical). Paralogues in human: RNY1 (90% identical), Y_RNA (90% identical), Y_RNA (88% identical), Y_RNA (87% identical), Y_RNA (86% identical), Y_RNA (85% identical), RNY1P11 (84% identical), Y_RNA (84% identical), Y_RNA (83% identical), RNY1P8 (82% identical), Y_RNA (82% identical), RNY1P15 (81% identical), and 97 more.